CD274 (CD274 molecule)
Description:
Plays a critical role in induction and maintenance of immune tolerance to self. As a ligand for the inhibitory receptor PDCD1/PD-1, modulates the activation threshold of T-cells and limits T-cell effector response. Through a yet unknown activating receptor, may costimulate T-cell subsets that predominantly produce interleukin-10 (IL10). Can also act as a transcription coactivator: in response to hypoxia, translocates into the nucleus via its interaction with phosphorylated STAT3 and promotes transcription of GSDMC, leading to pyroptosis. The PDCD1-mediated inhibitory pathway is exploited by tumors to attenuate anti-tumor immunity and escape destruction by the immune system, thereby facilitating tumor survival. The interaction with PDCD1/PD-1 inhibits cytotoxic T lymphocytes (CTLs) effector function (By similarity). The blockage of the PDCD1-mediated pathway results in the reversal of the exhausted T-cell phenotype and the normalization of the anti-tumor response, providing a rationale for cancer immunotherapy (By similarity).
Synonyms: PD-L1; hPD-L1; B7-H1; B7H1; PDCD1L1; PDCD1LG1; PDL1; B7-H; ADMIO5
Tractability: Small molecule: a structure with a bound ligand is known; a high-quality ligand is known; it has a binding pocket of medium quality. Antibody: an approved drug acts on it; UniProt places it where antibodies can reach, with high confidence; its Gene Ontology location is reachable by antibodies, with high confidence; UniProt predicts a signal peptide or a membrane-spanning region. PROTAC: it is named in the literature on targeted protein degradation; UniProt records ubiquitination sites on it; a small molecule that binds it is known. Other modalities: a drug acting on it is in phase 2 or 3 trials.
Chemical probes: CA-170 (high quality), INCB-086550
Gene: Protein-coding gene on chromosome 9 (5,450,503 to 5,470,566, forward strand). Ensembl gene ENSG00000120217.
Subcellular location: Cell membrane; Early endosome membrane; Recycling endosome membrane; Nucleus; Cell membrane (Isoform 1); Endomembrane system (Isoform 2); Secreted (Isoform 4)
Subcellular location (Human Protein Atlas): Nuclear speckles; Nucleoplasm; Plasma membrane; Predicted to be secreted
Pathways (Reactome):
Immune System: AMPK-induced ERAD and lysosome mediated degradation of PD-L1(CD274); Co-inhibition by PD-1; GSK3B-mediated proteasomal degradation of PD-L1(CD274); PD-L1(CD274) glycosylation and translocation to plasma membrane; Regulation of PD-L1(CD274) transcription; Regulation of PD-L1(CD274) translation; SPOP-mediated proteasomal degradation of PD-L1(CD274)
Signal Transduction: STAT3 nuclear events downstream of ALK signaling
Gene Ontology:
Molecular function: protein binding; receptor ligand activity; transcription coactivator activity
Biological process: cell surface receptor signaling pathway; immune response; negative regulation of activated T cell proliferation; negative regulation of CD4-positive, alpha-beta T cell proliferation; negative regulation of CD8-positive, alpha-beta T cell activation; negative regulation of interleukin-10 production; negative regulation of T cell activation; negative regulation of T cell mediated immune response to tumor cell; negative regulation of T cell receptor signaling pathway; negative regulation of tumor necrosis factor superfamily cytokine production; negative regulation of type II interferon production; positive regulation of activated CD8-positive, alpha-beta T cell apoptotic process; positive regulation of interleukin-10 production; regulation of activated CD4-positive, alpha-beta T cell apoptotic process; regulation of activated T cell proliferation; regulation of T cell apoptotic process; response to cytokine; signal transduction; T cell costimulation; TRIF-dependent toll-like receptor signaling pathway; cellular response to lipopolysaccharide; negative regulation of T cell proliferation; positive regulation of T cell proliferation; positive regulation of DNA-templated transcription
Cellular component: early endosome membrane; endomembrane system; extracellular exosome; extracellular region; nuclear speck; nucleoplasm; nucleus; plasma membrane; recycling endosome membrane; cytosol; endoplasmic reticulum membrane; external side of plasma membrane; Golgi membrane
Genetic constraint (gnomAD): Loss-of-function variants: 4 observed, 19.25 expected, observed/expected ratio (o/e) 0.21, 90% interval 0.1 to 0.48. The upper end of that interval is the gene's LOEUF score, 0.48, which puts it in group 2 of 6, group 1 being the genes least tolerant of losing a copy. Missense variants: 242 observed, 261.89 expected, observed/expected ratio (o/e) 0.92, 90% interval 0.83 to 1.03. Synonymous variants: 117 observed, 99.24 expected, observed/expected ratio (o/e) 1.18, 90% interval 1.01 to 1.38.
Homologues: Orthologues: chimpanzee CD274 (99% identical), macaque CD274 (92% identical), rabbit CD274 (78% identical), dog CD274 (75% identical), pig CD274 (72% identical), guinea pig CD274 (70% identical), rat Cd274 (70% identical), mouse Cd274 (69% identical). Paralogues in human: PDCD1LG2 (31% identical), CD86 (18% identical), CD80 (16% identical), RNF135 (9% identical), RFPL4A (7% identical), RFPL4AL1 (7% identical), RFPL1 (6% identical), RFPL3 (6% identical), RFPL2 (6% identical), RNF152 (4% identical), RFPL4B (4% identical), SPRYD4 (3% identical).
Diseases named in the same sentence as CD274 in open-access papers:
CD274 is named in the same sentence as 1,250 diseases in open-access papers, as found by Europe PMC text mining. Sharing a sentence is not in itself a finding about the gene and the disease. The quoted sentences say what the papers report.
melanoma (3,798 papers, 2012 to 2026). A malignant, usually aggressive tumor composed of atypical, neoplastic melanocytes. "Based on the analysis of the relationship between the model and clinicopathological characteristics, the risk score was significantly associated with the Clark stage of melanoma patients and CD274 expression." (PMID 40909968, 2025). "In a melanoma-bearing mouse model, circadian oscillations were reported in PD-1, Pdcd1, and in the PD-L1-encoding Cd274 gene." (PMID 37626878, 2023). "HDAC8 inhibition upregulates HOXA5/STAT3-mediated transcriptional activation of PD-L1 encoding gene, CD274, thereby enhancing anti-tumor T-cell response in melanoma cells." (PMID 36231123, 2022). "A CD274 miRNA score was generated, which was associated with disease progression and reduced survival of melanoma patients." (PMID 35802807, 2022). "Expression of CD274 ligands on tumor cells was found to contribute to tumor immune evasion and, in mouse models, antibody-mediated blockade of CD274 caused suppression of transplanted melanoma tumor growth." (PMID 34067485, 2021). "Melanoma and breast cancer both demonstrated that high expression of CD274 was significantly associated with patient survival and showed largely the same pattern for PDCD1." (PMID 34067485, 2021). "Programmed death-ligand 1 (PD-L1; encoded by the CD274 gene), a targeted protein in immunotherapy for malignant melanoma, could be an immunotherapy target in lung adenocarcinoma." (PMID 33446784, 2021). "Specifically, PD-L1 (CD274) mRNA was detected in melanoma cells, along with CD40 and B7-H3 (CD276) mRNAs." (PMID 40647495, 2025). "In BRAF-mutant melanomas, loss of the CDKN2A gene is typical, but amplification of MITF and CD274 (coding for PD-L1; programmed death ligand 1) is relatively common." (PMID 40361349, 2025). "Among the various immunotherapeutic approaches, blockade of immune checkpoint proteins, specifically PD-1/PD-L1 (CD279/CD274), has shown impressive effectiveness in various cancer types, including melanoma, lung cancer, and colorectal cancer." (PMID 38243170, 2024). "Given the efficacy of PD-L1 and CTLA4 inhibitors in various cancers, especially in melanoma and certain subsets of breast and cervical cancers, a bispecific antibody targeting both CD274 and CTLA4 has a strong rationale." (PMID 38713378, 2024). "CD56 (NCAM1) as well as CD274 (PD-L1) were only detected in metastatic melanoma cells and primarily on a protein-only level consistent with the overall detection pattern for these markers in liquid and solid cohorts." (PMID 37563418, 2023). "Immune checkpoint molecules (such as PDCD1, CD274, and CTLA4) and co-stimulatory molecules were also highly expressed in low-risk melanoma group (FDR-adjusted P < 0.05, one-sided Wilcoxon rank-sum test)." (PMID 37620409, 2023). "We further found that TET2/3, STAT1/3 and CD274 were more highly expressed in anti-PD1-treated Yumm1.7-derived melanoma cells than in similarly treated B16F10 cells." (PMID 36854755, 2023). "CD274, an important immunotherapeutic target, has achieved good results in non-small cell lung cancer, colorectal cancer and melanoma, and has also demonstrated prolonged overall survival in several phase II clinical trials in glioma." (PMID 38022536, 2023). "Support for targeting PD-L1 by ICI therapy in melanoma can be seen from an analysis of the TCGA-Melanoma datasets (TCGA-SKCM), where high expression of PD-L1 (CD274) is associated with better OS." (PMID 37156818, 2023).
melanoma (continued). "In this study, we screened a human miRNA library and identified miRNAs affecting the expression of ICMs NT5E, ENTPD1, and CD274 in the human tumor cell lines SK-Mel-28 (melanoma) and MDA-MB-231 (breast cancer)." (PMID 37409119, 2023). "Intriguingly, in the three melanoma anti-PD-1 cohorts included in this meta-analysis, CD274 (coding for PD-L1) was a further predictive marker." (PMID 35174087, 2022). "The constitutive expression of the miRNA candidates identified in this study differs to a certain extent between CD274‐positive and CD274‐negative melanoma lesions, with higher levels in the latter." (PMID 35802807, 2022). "MiRNAs resulting in less than a 10% reduction of CD274 expression in the mel1379 melanoma model were attributed a score of 1 (e.g., miR‐29a), while miRNAs reducing the CD274 expression level up to 20% or >20% were scored 2 (e.g., miR‐181b) or 3, respectively." (PMID 35802807, 2022). "The created PDM scoring system based on the functional efficiency of the identified miRNA candidates on the CD274 surface expression have a very strong prognostic value in our small cohort of melanoma patients." (PMID 35802807, 2022). "In A375 melanoma cells, knockdown of CD274, MCL1, and JUNB decreased cell survival, and in OAW28 ovarian cystadenocarcinoma cells, knockdown of MCL1 and JUNB decreased cell survival." (PMID 35338135, 2022). "Both the CD8+ T cell infiltration and PDM score were analysed regarding their ability to predict CD274 expression in the melanoma patients analysed." (PMID 35802807, 2022). "In order to determine the possible regulatory effects of the identified miRNAs on CD274 expression in vitro, melanoma cells were transfected with respective selected miRNA mimics." (PMID 35802807, 2022). "These miRNAs suppress the expression and function of CD274 upon transfection in melanoma cell lines and are of prognostic value for melanoma patients." (PMID 35802807, 2022). "HDAC6 causes STAT3 phosphorylation, where HDAC6 and phospho-STAT3 are then recruited to the CD274 promoter, mediating the upregulation of PD-L1 in melanoma." (PMID 34088360, 2021). "Hyperactivation by genomic mutations in oncogenic growth-signaling molecules, such as MAPK, PI3K, and the epidermal growth factor receptor (EGFR), can also enhance CD274 expression in malignant melanoma, NSCLC, and gallbladder cancer." (PMID 34572136, 2021). "It is interesting to note that for breast cancer, renal cancer, and melanoma, high CD274 expression was statistically significantly beneficial for patients." (PMID 34067485, 2021). "Strikingly, for the patient cohorts and cancer types selected, high CD274 expression appeared to be beneficial for breast cancer, melanoma, and renal cancer patients." (PMID 34067485, 2021). "PD-L1 (also known as CD274 or B7-H1) is highly expressed in various types of cancers, including melanoma, lymphoma, lung cancer, bladder cancer, and kidney cancer." (PMID 34829931, 2021). "We found that, as opposed to a continuum from low to high of CD274 (PD-L1 mRNA) expression, the CD274 expression in the melanoma cell lines was either at a low level (yet inducible, hence PDL1IND), or at a constitutively high level (PDL1CON)." (PMID 34503064, 2021). "CD274 Gene codes for Programmed death-ligand 1 (PD-L1) which is currently the target of several large trials showing substantial benefit with anti-PD-L1 for late-stage melanoma." (PMID 34589115, 2021). "Accumulating evidence confirms that CD274 promoter methylation determines PD-L1 expression and predicts the survival of melanoma patients, NSCLC, head, and neck squamous cell carcinomas (HNSCC) CRC." (PMID 34088360, 2021). "Individual immunotherapy panel markers CD274, PDCD1LG2, CD8A, IRF1 and a combined L1/L2 mRNA levels show promising associations with melanoma immunotherapy outcome." (PMID 31533832, 2019).
melanoma (continued). "It has been reported that CD274 is induced on murine melanoma cells upon communication with BM-derived CD11b+ cells BM-derived immune cells." (PMID 28423491, 2017). "In particular, blocking antibodies for PD-1 (PDCD1) or its ligand PD-L1 (CD274) were shown to have clinical efficacy in the treatment of melanoma and lung cancer." (PMID 28474673, 2017). "The introduction of monoclonal antibodies (MAbs) that block the checkpoint receptor programmed death receptor (PD1) and its ligand (PD-L1/CD274/B7-H1) in the treatment of melanoma has been a major breakthrough in the treatment of this disease." (PMID 25844720, 2015). "It should be noted that PD-L1 (CD274) amplified melanoma is certainly a tumor that may be hypersensitive to immunotherapy." (PMID 40361349, 2025). "Furthermore, high expression of CD274, encoding PD‐L1, was associated with an IRE1 alpha‐dependent gene signature in human melanoma samples." (PMID 40035165, 2025). "Since then, inhibitors targeting programmed cell death protein 1 (PD-1 or CD279) and its ligand (PD-L1 or CD274) have gained approval for a broadening array of solid tumors, including melanoma, renal cell carcinoma (RCC), non-small cell lung carcinoma (NSCLC), and urothelial carcinoma, among others." (PMID 40761787, 2025). "Thus, our findings provide evidence that ETV4 is a key transcription factor promoting CD274 gene transcription in melanoma cells." (PMID 41502516, 2025). "In addition, correlation analysis of seven clinical characteristics and CD274 expression demonstrated that major differences existed in Clark stage and CD274 expression in melanomas (p = 0.019 and p < 0.001, respectively)." (PMID 40909968, 2025). "Cutaneous melanoma patients with ARID2 mutation showed significant enrichment with immune checkpoint infiltration markers, including high expression of CD274 (also known as PD-L1), a well-established response marker for immunotherapy." (PMID 38341515, 2024). "While therapeutic STING agonism coordinately enhanced expression of the Arg2, Isg15, Nos2, and Pdl1 (Cd274) immuno-suppressive/regulatory ISGs in both melanoma models, Cox2/Ptgs2 expression was selectively upregulated by ADU-S100 treatment only in the B16 model." (PMID 38312842, 2024). "Indeed, we identified increased IRF1 and CD274 mRNA levels after exposure of melanoma cells to IFNγ, correlating with increased membrane PD-L1." (PMID 39237877, 2024). "In contrast to HAVCR2 and LAG3, the dynamics of PDCD1 and CD274 did not coincide with the dynamics of CTL exhaustion, suggesting a relatively minor role for PD-1/PD-L1 as determinants of CTL exhaustion in the B16F10 melanoma model, at least at late stages of anti-tumour immune responses." (PMID 37182110, 2023). "Furthermore, an inverse expression of three CD274‐regulating miRNAs and CD274 was demonstrated in melanoma lesions." (PMID 35802807, 2022). "Since an important requirement for the outcome of the miTRAP analysis is the selection of a suitable cell line, the CD274 mRNA and protein expression profiles of 49 different melanoma cell lines were monitored regarding a discordant CD274 expression as indicator of a post‐transcriptional regulation." (PMID 35802807, 2022). "Finally, the prognostic value of the suggested comPDM signature was increased by combining the PDM score, the CD274 expression as well as the CD8+ T cell infiltrate in the melanoma lesions." (PMID 35802807, 2022). "The prediction performances of ACAP1 were better than TIDE, MSI, TMB, and CD274 in >50% of melanoma cohorts and achieved a high prediction accuracy of ICT response with an AUC > 0.7, predicting a strong likelihood of positive response to immunotherapy, in four cohorts." (PMID 36497434, 2022).